RARA-AS1 (RARA antisense RNA 1)
Gene: Long non-coding RNA gene on chromosome 17 (40,340,867 to 40,343,136, reverse strand). Ensembl gene ENSG00000265666.
Diseases named in the same sentence as RARA-AS1 in open-access papers:
RARA-AS1 is named in the same sentence as 1 disease in open-access papers, as found by Europe PMC text mining. Sharing a sentence is not in itself a finding about the gene and the disease. The quoted sentences say what the papers report.
cancer (1 paper, 2023). A tumor composed of atypical neoplastic, often pleomorphic cells that invade other tissues. "This study investigates the role of RARA Antisense RNA 1 (RARA-AS1) in cancer and its implications for diagnosis and treatment." (PMID 37833349, 2023).